PIK3CA (phosphatidylinositol-4,5-bisphosphate 3-kinase catalytic subunit alpha)
Diseases named in the same sentence as PIK3CA in open-access papers (continued):
Sharing a sentence is not in itself a finding about the gene and the disease.
CLOVES syndrome (26 papers, 2013 to 2026). A syndromic disease characterized by Congenital Lipomatous Overgrowth, progressive, complex and mixed truncal Vascular malformations, Epidermal nevi, and Skeletal anomaly. "Congenital lipomatous overgrowth, vascular epidermal nevi, and skeletal abnormalities (CLOVES) syndrome is a rare genetic disorder caused by somatic activating mutations in the PIK3CA gene that arise during embryonic development." (PMID 41800036, 2026). "CLOVES syndrome is part of the PIK3CA-related overgrowth spectrum, caused by somatic, post-zygotic activating mutations in the PIK3CA gene." (PMID 40861611, 2025). "Another disease associated with PIK3CA mutations, CLOVES syndrome, has been reported to have an increased risk of developing Wilms tumor." (PMID 38378686, 2024). "CLOVES syndrome (OMIM# 612918) is a rare overgrowth disorder resulted from mosaic gain-of-function mutations in the PIK3CA gene." (PMID 34074347, 2021). "The CLOVES syndrome is an overgrowth disease arising from mosaic activating somatic mutations in the PIK3CA gene." (PMID 33431926, 2021). "Sequencing data showed the presence of PIK3CA (NM_006218) c.3140A>G (H1047R) gain-of-function mutation (11% mosaicism), confirming the diagnosis of CLOVES syndrome in our patient." (PMID 34568242, 2021). "Mosaic mutations in hot spot codons of PIK3CA (542, 545, 1047) account for the majority of the individuals with CLOVES syndrome." (PMID 34074347, 2021). "In this study, we reported a patient with CLOVES syndrome caused by a somatic frameshift mutation c.3206_3207insG in PIK3CA which results in gain of function by provoking the PI3K/AKT/mTOR pathway." (PMID 34074347, 2021). "CLOVES syndrome is caused by a postzygotic activating PIK3CA mutation, and is considered by many to be on a spectrum with other disorders characterized by PIK3CA somatic mutations." (PMID 33194900, 2020). "The lipomatous overgrowths were successfully resected, and subsequent genetic analysis revealed a heterozygous, pathogenic, somatic variant in the PIK3CA gene, confirming our suspicion of CLOVES syndrome." (PMID 33145141, 2020). "Recently, groundbreaking results were obtained with the administration of PIK3CA inhibitors to patients with CLOVES syndrome, a genetic disorder resulting from somatic gain-of-function variants in PIK3CA." (PMID 31444548, 2019). "CLOVES syndrome is generally caused by somatic mosaicism of gain-of-function variants in PIK3CA (3q26.32)." (PMID 31263565, 2019). "Support for a non-cell-autonomous mechanism underlying hamartoma formation comes from the demonstration that CLOVES syndrome patients, who also develop hamartomas, have activating mutations in PIK3CA, which phenocopies PTEN loss." (PMID 29716894, 2018). "Congenital lipomatous overgrowth, vascular malformations, epidermal nevi, and skeletal anomalies (CLOVES) syndrome is a rare, sporadic overgrowth disorder caused by a post-zygotic mutation in the phosphatidylinositol-4,5-bisphosphate 3-kinase catalytic subunit alpha (PIK3CA) gene." (PMID 40861611, 2025). "HME patients, sometimes associated with CLOVES syndrome, might represent good candidates for PIK3CA inhibitors-based treatment." (PMID 31444548, 2019). "Recently a syndrome comprising congenital lipomatous overgrowth, vascular malformations, epidermal nevi, and skeletal/spinal abnormalities (CLOVES syndrome) has been found to involve postzygotic mutations and identified somatic mosaic mutations in PIK3CA in affected individuals." (PMID 24497998, 2014). "In Cloves Syndrome mutations occur in PIK3CA gene in a range of 3-30%." (PMID 23768168, 2013).
CLOVES syndrome (continued). "Recent success has been achieved using alpelisib to treat PIK3CA-associated disorders, including CLOVE syndrome (MIM: 612918); however, this is only applicable to individuals harboring a PIK3CA mutation." (PMID 38141607, 2024). "Diffuse capillary malformation with overgrowth, Klippel–Trenaunay syndrome, CLAPO syndrome, CLOVES syndrome, and megalencephaly-capillary malformation belong to the PIK3CA-related overgrowth." (PMID 34692608, 2021). "Researchers have recently identified activating mutations in PIK3CA in isolated LMs as well as overgrowth syndromes such as KTS and CLOVES syndrome, and collectively termed these diseases PIK3CA-related overgrowth spectrum (PROS)." (PMID 30947262, 2019). "Somatic PIK3CA mutations also occur frequently across many cancer types; however, evidence linking CLOVES syndrome to increased cancer risk is not conclusive." (PMID 41800036, 2026). "In this case, we could not detect somatic PIK3CA alterations in this patient's urothelial carcinoma and suggest that it is unrelated to CLOVES syndrome." (PMID 41800036, 2026).
colorectal tumors (25 papers, 2005 to 2025). "Other than RAS genes that predict anti-EGFR sensitivity, PIK3CA mutations have prognostic implication in colorectal tumors." (PMID 37483495, 2023). "Studies characterizing patients with PIK3CA-mutated CRC have suggested that tumors exhibiting these mutations are more likely to be located in the proximal colon, and to exhibit KRAS mutations than PIK3CA-wildtype colorectal tumors." (PMID 26337942, 2015). "The frequency of B-Raf and PIK3CA mutations in colorectal tumours has been estimated between 10 and 17% and between 10 and 25%, respectively." (PMID 21712828, 2011). "V600E mutations in B-Raf are the most prevalent and therefore the most commonly analysed mutations in colorectal tumours, whereas exons 9 (codons 542 and 545) and 20 (codons 1023 and 1047) have been shown to harbour ∼80% of all PIK3CA mutations." (PMID 21712828, 2011). "This PIK3CA mutation resides in a hotspot exon for mutations that has been previously reported in a MSI colorectal tumour." (PMID 18782444, 2008). "In this seminal paper, the authors initially analysed the sequence of eight PI3K and eight PI3K-like genes in a relatively small number of primary colorectal tumours and discovered that PIK3CA was the only gene harbouring somatic mutations." (PMID 16449998, 2006). "Conversely, PIK3CA mutations are more often observed in colorectal tumors from AFA individuals." (PMID 38836758, 2024). "PIK3CA mutations have been detected in 10 to 32% of colorectal tumors." (PMID 35723313, 2022). "However, mutations in the K-Ras, B-Raf or PIK3CA genes, common in colorectal tumours, result in structural changes in the corresponding proteins, altered effector binding and permanent activation of downstream signalling pathways, independent of EGFR blockade." (PMID 21712828, 2011). "In colorectal tumours, K-Ras mutations have been associated with a more aggressive tumour phenotype and reduced patient survival, whereas B-Raf and PIK3CA mutations have also been associated with both disease pathogenesis and prognosis." (PMID 21712828, 2011). "Mutations in K-Ras, B-Raf and PIK3CA were identified by both dideoxy and quantitative pyrosequencing-based methods in a cohort of unselected colorectal tumours (n=102), and pyrosequencing-based mutation calls correlated with various clinico-pathological parameters." (PMID 21712828, 2011). "Lastly, oncogenic PIK3CA mutations reduce apoptosis and increase tumor invasion by activating the AKT signaling pathway, thereby promoting the occurrence of colorectal tumors." (PMID 39555098, 2024). "In our study, PIK3CA mRNA levels decreased in colorectal tumor tissues compared to control, while in peripheral blood samples increased compared to the control group." (PMID 33237662, 2021). "In our study, it was found that PIK3CA mRNA levels decreased in colorectal tumor tissues compared to control, while it increased in peripheral blood compared to the control group." (PMID 33237662, 2021). "Mutations were identified in 66.4% of colorectal tumors with KRAS (41.5%) and PIK3CA (14.7%) being among the most frequently mutated genes, in line with previous studies." (PMID 32087721, 2020). "This was derived from an individual carrying a quadruple wild-type (KRAS, NRAS, BRAF and PIK3CA) colorectal tumour, and thus recapitulates the molecular profile of patients sensitive to anti-EGFR antibodies." (PMID 26392303, 2015).
colorectal tumors (continued). "The same experimental strategy was then applied to an independent PDX that was also derived from a quadruple wild-type (KRAS, NRAS, BRAF and PIK3CA) colorectal tumour and was sensitive to EGFR blockade." (PMID 26392303, 2015). "First, signature genes characteristic of the tumor types in question, such as APC in colorectal tumors and ARID1A, PIK3CA, and PTEN in non-serous ovarian carcinomas were well represented." (PMID 29296220, 2017).
esophageal cancer (25 papers, 2012 to 2025). A primary or metastatic malignant neoplasm involving the esophagus. "In contrast, in esophageal cancer, PIK3CA mutations are regarded as independent favorable prognostic factors." (PMID 40508087, 2025). "In this study, we screened 64 ESCC tissue specimens for PD-L1 expression, HPV infection, MSI/dMMR, and mutations in the KRAS, BRAF, or PIK3CA genes to determine their prognostic value in esophageal cancers." (PMID 33054840, 2020). "There are limited studies that have evaluated PIK3CA mutation, which has an incidence of 1.5–21%, in esophageal cancers." (PMID 33054840, 2020). "In this study, PIK3CA mutation was detected in 12.5% of esophageal cancers and was associated with female or younger patients (≤60 years) lacking mutations in the KRAS and BRAF genes." (PMID 33054840, 2020). "This is the first report on the presence of PIK3CA mutations in esophageal cancer associated with chagasic megaesophagus." (PMID 30619505, 2018). "We then evaluated the clinicopathological and molecular characteristics of PIK3CA mutations in esophageal cancer." (PMID 30115035, 2018). "The prevalence and distribution of PIK3CA mutations found in our study by ME-Liquidchip (11.3%) were in agreement with previous data reported in esophageal cancer." (PMID 25106743, 2014). "PIK3CA mutations on exons 9 and 20 were analyzed in 106 esophageal carcinoma patients by Sanger sequencing, pyrosequencing, ME-Liquidchip." (PMID 25106743, 2014). "The detection of PIK3CA mutation in ESCCs may suggest that PIK3CA mutation may be involved in the development and progression of esophageal cancers, especially in female and younger patients (≤60 years) who are not commonly affected by ESCCs." (PMID 33054840, 2020). "However, the combined analyses revealed that the PIK3CA mutation in PD-L1-negative esophageal cancers was significantly correlated with poor survival." (PMID 33054840, 2020). "In the future, PIK3CA mutations may be potential targets in therapeutic development of esophageal cancer." (PMID 30115035, 2018). "Our study provided profiles of cancer-related genes in Japanese patients with esophageal cancer by next-generation sequencing using surgically resected formalin-fixed, paraffin-embedded tissue, and identified the PIK3CA mutation as a favorable prognosis biomarker." (PMID 30115035, 2018). "A recent report extends previous studies suggesting that the acquisition of PIK3CA mutations may be an important molecular event in the etiology of esophageal cancer (EC) and the mutations are associated with their clinical outcome." (PMID 25106743, 2014). "The PIK3CA gene mutation was found to associate with prognosis and might affect molecular targeted therapy in esophageal carcinoma (EC)." (PMID 25106743, 2014). "In the PD-L1-negative esophageal cancers, patients with PIK3CA-mutated tumors exhibited poorer OS and DFS than patients with PIK3CA-wild-type tumors (P = 0.006 and P = 0.002, respectively)." (PMID 33054840, 2020). "To further characterize the PIK3CA mutation and wild-type, we also investigated the clinicopathological characteristics of esophageal cancer patients with respect to PIK3CA status." (PMID 30115035, 2018).
esophageal cancer (continued). "Our study provides comprehensive genomic profiling of resected esophageal cancer by NGS using surgically resected FFPE tissue and identified PIK3CA mutations as a favorable prognosis biomarker." (PMID 30115035, 2018). "Alterations in PIK3CA are also present in gastric (2–25%), endometrial (16–51%), head and neck (6–21%), and esophageal cancers (5–21%)." (PMID 40508087, 2025). "XLOC was also upregulated in esophageal cancer tissues, and further experiments showed that XLOC_001659/miR-490-5p/PIK3CA might be a new molecular target for esophageal cancer." (PMID 40191723, 2025). "However, MSI/dMMR, RAS/BRAF/PIK3CA mutations, and HPV status have been rarely investigated in esophageal cancers." (PMID 33054840, 2020). "For esophageal carcinoma, one study demonstrated 26.7% of PIK3CA gene amplification in ESCC." (PMID 27095573, 2016). "In a previous study, the minor allele homozygous AA of PIK3CA:rs6443624 was associated with risk of recurrence, but none of these PIK3CA SNPs were found to correlate with recurrence in esophageal cancer patients." (PMID 24945674, 2014). "Furthermore, PIK3CA mutations were always found in esophageal cancer and further functional analyses of the mutations are warranted to determine whether or not they may be potentially useful targets of therapy for esophageal cancer." (PMID 24422746, 2014).
liver cancer (25 papers, 2006 to 2025). An epithelial or non-epithelial malignant neoplasm that arises from the liver. "A study by AlGabbani indicates that people with chronic schistosomiasis are susceptible to PIK3CA (phosphoinositide-3-kinase-catalytic-alpha) gene mutations, which can eventually cause liver cancer and hepatocyte fibrosis." (PMID 41471957, 2025). "The risk of PIK3CA gene mutations in patients with chronic Schistosomiasis is higher, which can result in hepatocyte fibrosis and liver cancer eventually." (PMID 36998605, 2023). "Another recent study demonstrated a very high rate (36%) of PIK3CA somatic mutations in liver cancer." (PMID 16449998, 2006). "It is now evident that cancers of the liver, colon and breast harbour the most PIK3CA mutations with average mutational frequencies (across the reported studies) of 36, 26 and 25%, respectively." (PMID 16449998, 2006). "For example, miR-375 inhibits the development of osteosarcoma via targeting PIK3CA; In liver cancer, miR-124 impedes the proliferation of cancer cells via targeting PIK3CA." (PMID 33509213, 2021). "In support of our observations, studies have shown that PIK3CA is mutated in up to 30% of CRC as well as other tumors such as breast, ovarian, and liver cancer typically leading to activation of the PI3K/AKT/mTOR signaling pathway." (PMID 24943349, 2014). "circ-ZEB1 could enhance PIK3CA expression via miR-199a-3p silencing and affecting liver cancer progression." (PMID 39802932, 2025). "Moreover, we selected the regular hepatic cell line (HL-7702) and HCC cell lines (Huh-7, HCC-LM3, MHCC-97H, SMMC-7721) to perform RT-qPCR, revealing the expression of circ-ZEB1 and PIK3CA in liver cancer cell lines." (PMID 35277182, 2022). "In addition, the expression of PIK3CA and mTOR also correlated with poor overall survival in liver cancer patients." (PMID 34716294, 2021). "Analyses of TCGA databases show the genetic alteration of PIK3CA and mTOR in liver cancer patients." (PMID 34716294, 2021). "Correlation analysis discovered that NR0B2 expression is negatively correlated with PI3K pathway genes PIK3CA and PIK3CG in liver cancer tissues." (PMID 34055653, 2021). "NR0B2 expression is conversely correlated with tumor-infiltrating B-cells, CD8+ T cells, and dendritic cells, as well as PIK3CA and PIK3CG gene expression in liver cancer tissues." (PMID 34055653, 2021). "Fucoidan exerts its anti-liver cancer effect primarily by downregulating mRNA expression levels of target genes including AKT1, PI3K, PIK3R1, PIK3CA and other targets, inhibition of PI3K/Akt signaling pathway activation, and suppressing HepG2 cell proliferation." (PMID 40740310, 2025). "In addition, NR0B2 expression negatively correlated with immune infiltration and PIK3CA and PIK3CG gene expression in liver cancer tissues." (PMID 34055653, 2021).